IL4 (interleukin 4)
Diseases named in the same sentence as IL4 in open-access papers (continued):
Sharing a sentence is not in itself a finding about the gene and the disease.
tumor (2,127 papers, 1991 to 2026). "Accelerated tumor growth in the Gsdmdfl/fl CD4cre mice was associated with decreased cytokine levels, including IL-2, IL-12, IL-4, and IL-10." (PMID 40759573, 2025). "Although we have described tumor phenotypes where durable control can be achieved with a combination of IL-4/IFN-I, the underlying mechanisms of this response are yet to be fully elucidated." (PMID 40367186, 2025). "Th2 polarization in the tumor microenvironment has been implicated in tumor-promoting processes mediated by IL-4 and IL-13 signaling, which enhance immune evasion, tissue remodeling, and lymphangiogenesis through M2-like macrophage activation." (PMID 41383514, 2025). "IL-12, IL-2, and IFN-γ promote Th1 differentiation, which supports antitumor immunity, whereas IL-4, IL-5, and IL-10 drive Th2 differentiation, which is associated with tumor growth and immune suppression." (PMID 40429961, 2025). "In lung and renal cancers, elevated IL-4/IL-13 levels are linked to increased tumor growth, metastatic potential, and poor clinical outcomes." (PMID 40497988, 2025). "DSG2 knockdown suppressed IL-4 and GM-CSF expression, which promoted the enrichment of tumour-associated macrophages to establish a supportive PCSC niche." (PMID 40615400, 2025). "M2-like tumor-associated macrophages (TAMs), which are abundant in MF lesions, secrete high levels of IL-4, IL-13, and TGF-β." (PMID 40864740, 2025). "While TNF-α is a proinflammatory cytokine, crucial for promoting a strong and functional type 1 anti-tumor immune response, IL-33 and IL-4 are associated with immunosuppression and tumor promotion." (PMID 40943444, 2025). "Immunosuppressive cytokines such as IL-4 and IL-10 promote differentiation of monocytes to tumor-associated macrophages and regulatory T cells, thereby inhibiting T-cell effector functions and contributing to a protumorigenic environment." (PMID 40807278, 2025). "The effects of IL-4, IL-13, and IL-17A on tumor immunity are controversial, as various studies have shown they are associated with tumor progression or tumor suppression." (PMID 39743545, 2025). "In one study, it has been reported that IL4 + MCs are linked to preferred Th2 polarization in tumor-draining LNs by enriching within the sinus and T cell zones of tumor-draining LNs associated with cold triple-negative breast cancer tumors." (PMID 40175843, 2025). "In contrast, M2 polarization, associated with tumor promotion, is activated by signals like IL-4, IL-10, and TGF-β, primarily through the JAK/STAT6, PI3K/AKT/mTOR, and TGF-β/SMAD pathways, promoting tissue repair, immune suppression, and angiogenesis." (PMID 40330466, 2025). "Not only did we observe more pro-tumorigenic macrophages and IL-4 in MIC β1 integrin-deficient recurrent tumors but spatial analyses also revealed that they are located adjacent to proliferating epithelial tumor cells." (PMID 39448577, 2024). "In contrast, M2 polarization, induced by cytokines of the type 2 immune response, such as interleukin (IL)-13 and IL-4, has been associated with tissue repair and tumor-promotion." (PMID 38426089, 2024). "Tumor cells can also produce IL-4, which can activate tumor-associated macrophages (TAMs) and myeloid-derived suppressor cells (MDSCs), thus enhancing the invasion of tumors." (PMID 39221149, 2024). "Higher levels of IL-4 were associated with tumor cell resistance to pro-apoptotic signaling in an in vitro cancer model." (PMID 39456897, 2024). "Tumor-associated macrophages are often polarized to the M2-like type in response to IL-4, IL-10, IL-13, and other cytokines, favoring angiogenesis, dissemination, and immunosuppression." (PMID 39456647, 2024). "Although we were unable to identify the mechanism(s) underlying the upregulation of Dectin-1 in myeloid and tumor cells, it is reported that macrophages treated with IL-4 and IL-13 upregulate the expression of Dectin-1." (PMID 38668817, 2024).
tumor (continued). "On the other hand, IL-4 has been linked to reduced cell proliferation in colon, kidney, and breast cancers, highlighting its complex role in tumor biology." (PMID 39334861, 2024). "IL4, known to be capable of activating tumours, has also been shown to be associated with an increased risk of developing chronic renal disease." (PMID 39557632, 2024). "Compared to the IL-4 (interleukin 4)-treated control, the expression of iNOS (nitric oxide synthase), which causes tumor cell death, significantly increased after the nano-immunomodulator therapy, rising from 19.4% to 96.1% (76.7%)." (PMID 39596082, 2024). "The other type mainly occurs in the process of tumor proliferation and metastasis, and macrophages induced by IL-4 and IL-10 are polarized to the M2-like phenotype, which is called M2-like tumor-associated macrophages." (PMID 39596288, 2024). "Studies have indicated that it is associated with high expression of TGF-β, IL-4, IL-13, and IL-10, suppressing the inflammatory response and encouraging tumor angiogenesis and distant metastasis." (PMID 39108265, 2024). "IL-4, IL-5, and IL-13 are associated with the Th2 immune response, which can create an immunosuppressive environment that promotes tumor progression." (PMID 39456897, 2024). "Tregs within the tumor can produce cytokines such as IL-4, IL-10, and IL-13, causing monocytes to differentiate into tumor-associated macrophages (TAMs)." (PMID 39253716, 2024). "Cytokines such as IL-4 and IL-13 within the tumor microenvironment regulate the polarization of tumor-associated macrophages (TAMs) through downstream Stat6-dependent inhibition of Arg1, activation of PPARγ, and TSC1-mediated inhibition of mTOR." (PMID 39676873, 2024). "M2 macrophages, as the primary expression form of tumor-associated macrophages, promote Th2 cell differentiation through the induction of IL-4, IL-13, and other cytokines and secrete IL-10, TGF-β to suppress inflammatory cytokines." (PMID 39104717, 2024). "Tregs in the tumor produce cytokines such as IL-4, IL-10, and IL-13, which cause monocytes to differentiate into tumor-associated macrophages (TAMs)." (PMID 39253716, 2024). "Conversely, M2 macrophages, polarized by IL-4, are associated with tissue repair, anti-inflammatory responses, and tumor promotion, marked by arginase (ARG-1), IL-10, TGF-β, and the mannose receptor (CD206)." (PMID 39795180, 2024). "IL-4 is known to induce M2 macrophages which have immunosuppressive functions and have been linked to tumor progression." (PMID 39717106, 2024). "IL-10 and IL-4 are confirmed immunosuppressive cytokines associated with tumor growth and metastasis." (PMID 39439459, 2024). "Tumour-associated macrophages (TAMs), the M2 phenotype, are promoted within the tumour through hypoxia and the secretion of factors such as IL-4." (PMID 38399237, 2024). "Conversely, activation of STAT3 and STAT6 by IL-4 and IL-13 predominantly leads to polarization of macrophages towards the M2 phenotype, associated with immune suppression and tumor progression." (PMID 38745331, 2024). "Granulocyte-monocyte colony-stimulating factor (GM-CSF) and IL-4 cause the induced expression of PD-L2 on DCs, and thus promote immune-independent tumor progression." (PMID 38255322, 2024). "In the context of immune cells, IL4 signaling has been characterized as largely immunosuppressive and pro-tumorigenic, mediated by the previously discussed role it plays in polarizing tumor-associated macrophages to the M2 phenotype." (PMID 38731867, 2024). "Taken together, our study reveals an IFN-triggered IL-4/IL-6 cytokine network impacting on the phenotypes of tumor-associated macrophages." (PMID 36726024, 2023). "YY1 function is regulated through the IL-4/STAT6 signaling pathway in tumor-associated immune cells." (PMID 37762277, 2023). "It was documented that IL-4 administration or overexpression is associated with reduction of tumor growth, which was estimated in in vivo studies." (PMID 36376448, 2023).
tumor (continued). "Some studies have confirmed that Th2 cells expressing IL-13, IL-5, and IL-4 recruit M2-like tumor-associated macrophages and contribute to tumor angiogenesis by activating STAT-646–49." (PMID 37248248, 2023). "In contrast, in tumor-associated macrophages, IL4 creates an inflammation inhibitory microenvironment which in turn drives tumor growth and metastasis." (PMID 36610795, 2023). "Release of IL-1, IL-4 and IL-6 from mast cells was associated with elimination of tumour cells and rejection of tumours." (PMID 38137361, 2023). "A recent work further demonstrated that IL-4 polarized and tumor-associated macrophages show increased activity of protein kinase RNA-like ER kinase (PERK), which is required to sustain FAO and mitochondrial activity by promoting serine biosynthesis." (PMID 37740232, 2023). "Tumor-associated macrophages (TAMs) are among these immune subtypes and can be polarized to M2 by IL-13, IL-4, TGF-β, or IL-10, within the TME." (PMID 36860731, 2023). "IL4 derived from basophils, and cancer-associated fibroblast-secreted thymic stromal lymphopoietin induce tumor infiltration of Th2 cells and promote Th2 inflammation, which is related to the poorer survival in patients with PAAD." (PMID 36975441, 2023). "The characteristics of tumor-associated M2 macrophages are orchestrated by the action of IL-4, IL-10, IL-13, macrophage colony-stimulating factor 1 (CSF-1), CCL2, or VEGF-A." (PMID 38033495, 2023). "In the context of malignancies, IL-4 and IL-13 have been shown to induce polarization towards protumoral tumor-associated macrophages (TAM)." (PMID 38074683, 2023). "IL-4 produced by CD-25+ Th2 tumor-infiltrating cells transforms tumor-associated macrophages into producing high epidermal growth factor (EGF) levels, promoting metastasis." (PMID 35884974, 2022). "TNBC cells have also been observed to secrete interleukin (IL)-4, IL-10, and other factors to promote tumor-associated macrophage polarization toward M2, which is associated with fast tumor progression." (PMID 35432487, 2022). "In the early stage of tumor formation, an abnormal immune response caused by IL-4 promotes cancer cell mutation and DNA damage, thus promoting the occurrence and development of tumors." (PMID 35479514, 2022). "For example, cytokines in the TME, such as TNF-α, IL-6, and IL-8, are associated with angiogenesis and tumor metastasis, whereas IL-4, IL-13, and IL-10 are associated with immune response suppression." (PMID 35844605, 2022). "GM-CSF 1 IL-4 treatment caused BM (19.7 ± 7.5% of cells) and spleen (33.1 ± 6.9% of cells) M-MDSCs to significantly gain CD11c expression whereas tumor M-MDSCs were unresponsive to these treatments (1.5 ± 1.0% of cells)." (PMID 36480485, 2022). "The increased secretion of interleukin-4 was associated with macrophage-induced tumor growth and metastasis." (PMID 36138874, 2022). "In another study, increased expression of IL‐4/STAT6 signaling was associated with reduced tumor volume and weight, as well as the increased expression of apoptotic proteins." (PMID 35244291, 2022). "Hao-Wei Wang and Johanna A Joyce have summarized IL-4-induced gene sets in TAMs in mouse and human in their review named Alternative activation of tumor-associated macrophages by IL-4 Priming for protumoral functions." (PMID 36325334, 2022). "Tumor-specific Th2 cell responses are associated with tumor immune evasion, and Th2 cytokines such as IL-4 and IL-13 are implicated in the suppression of host immune effector responses to tumors." (PMID 36105094, 2022). "Subsequently, the tumor-associated macrophages (TAMs) promote angiogenesis, tumor progression, metastasis, and resistance to chemotherapy under the influence of IL-4, IL-10, or IL-13." (PMID 36295075, 2022). "Mechanistically, we find that FAK regulates interleukin-6, which can act in concert with interleukin-4 secreted by CD4 T-cells to drive elevated expression of PD-L2 on tumour-associated macrophages, dendritic cells and endothelial cells." (PMID 36138073, 2022).
tumor (continued). "Although an oversimplification, for charting purposes, the cytokines were split into three groups by their generalized tumor-destroying (IFN-γ, IL-2, and IL-5), tumor-promoting (IL-10 and IL-4), or SIRS-associated (IL-1β, IL-6, CXCL-1, and TNF-α) properties." (PMID 35465347, 2022). "IL-4, IL-10, and IL-13 signaling, along with significantly elevated tumor-associated transcription factor abnormalities, upregulation of IL-17 and Hif-1a pathways, and glucose metabolism pathway, was enriched in Mac3, which pointed to M2 characteristics." (PMID 35874770, 2022). "IL1β, IL-2, IL-12, TNF-α, and IFN-γ, known as Th1 cytokines, are associated with good prognosis in many malignancies, whereas Th2 cytokines (IL-4, IL-5, and IL-10) are associated with tumor growth and metastasis." (PMID 36090972, 2022). "The presence of IL-4 in the tumor microenvironment was also found to be associated with tumor promotion and poor prognosis." (PMID 36457849, 2022). "IL-33 deficiency or blockade led to reduced tumour Il4, Il6 and Il13 expression, and correlated with reduced tumour mast cells." (PMID 36263033, 2022). "Tumor-associated macrophages (TAMs) are shaped by chemokines such as IL-4, IL-10, and IL-13 to suppress antitumor immunity." (PMID 35493518, 2022). "M2 tumor-associated macrophages (TAMs) are stimulated by anti-inflammatory cytokines (IL4 and IL13) and enhance the tumor growth by down-regulation of the inflammatory response." (PMID 35736195, 2022). "In cancer, IL-4 functions in the tumor microenvironment to mediate pro-tumor activity by activating tumor-associated or myeloid-derived suppressor cell (MDSC) associated macrophages." (PMID 35525950, 2022). "These trans-differentiated astrocytes secrete IL-4 and polarize tumor-associated microglia to produce IGF-1, which in turn stimulates tumor progression by accelerating migration and adhesion." (PMID 36291792, 2022). "M2 macrophages are classically stimulated by cytokines IL-4, IL-13, IL-10, and M-CSF and are associated with reduction of inflammatory signals, resolution of the immune response, wound healing, and tumor promotion." (PMID 35264604, 2022). "In humans, high expression levels of IL4 are observed in breast tumors, which is associated with a Th2-skewed profile of tumor-infiltrating lymphocytes." (PMID 36077870, 2022). "IL-4 is a cytokine that polarizes T-lymphocyte differentiation towards Th2 cells and macrophages towards pro-tumoral (M2) phenotypes, leading to tumor escape caused by an unbalanced immune response." (PMID 36248816, 2022). "Interleukin (IL)-4-producing Th2 cells and IL-17-producing Th17 cells are mostly associated with tumor progression in several tumor entities." (PMID 35326515, 2022). "Lastly, IL-4-expressing CD4+ T cells were found to directly regulate tumor-associated macrophages (TAMs) in preclinical breast cancer models." (PMID 35335881, 2022). "High-resolution intravital imaging at the time of metastatic seeding showed reduced physical interaction between tumor cells and IL4rα-deficient macrophages, showing the dependence on IL4." (PMID 36077870, 2022). "Other inflammatory cytokines, such as toll like receptor 3(TLR-3), transforming growth factor β (TGF-β), IFN- α/β and IL-4/6/17/27 have been shown to enhance the expression of PD-L1 mRNA on tumor cells or tumor associated stromal cells." (PMID 36505487, 2022). "When macrophages are exposed to T helper 2 (Th2) cytokines (such as IL-4 and IL-13), they polarize into M2 macrophages and promote tumor growth, while tumor-associated macrophages (TAMs) are mainly characterized by M2 macrophages." (PMID 35601497, 2022). "Th2 cells can secrete multiple cytokines, such as IL-4, IL-5, IL-10, and IL-13, which are associated with inflammation and tumor-promoting functions." (PMID 36193495, 2022). "The presence of tumor-associated macrophages 2 (TAM2) with CD4+ T lymphocytes releasing IL4 and myeloid-derived suppressor cells (MDSCs) moves the TME in favor of tumor immune scape." (PMID 36552048, 2022).
tumor (continued). "Mechanistically, ICJ redirected M2-dominant polarization of tumor-associated macrophage in an IL-4-mTOR-dependent manner." (PMID 35027915, 2021). "The involvement of type 2 immunity in antitumor immune responses is reflected by studies showing that IFN-γ-deficient and, importantly, also mice deficient for the Th2 cytokines IL-4 and IL-5 show reduced tumor clearance." (PMID 34135885, 2021). "Th2 cells were suggested to play a central role in the development of primary tumors and metastases by secreting cytokines such as IL-4 and IL-13 that induce a tumor-promoting M2 or M2-like phenotype of tumor associated macrophages." (PMID 34868011, 2021). "(Th) 2 cells release cytokines such as IL-4, IL-5, and IL-10, and Tregs cells cause immune-suppression, thus eventually supporting tumor growth." (PMID 34439380, 2021). "Several proinflammatory cytokines such as TNF-α, IFN-α/β, TGF-β and IL-4/6/17/27 have been shown to induce the expression of programed death ligand 1 (PD-L1) in tumor cells and tumor-associated stromal cells." (PMID 33806053, 2021). "Since tumor-associated myeloid cells can inhibit immune cell functions, the observed decrease in Il-4 and Il-5 together with a tendency of Il-10 in TR2myKO mice suggests a possible reduced polarization of T cells." (PMID 34868988, 2021). "Since osteoclasts (OCs) were responsible for osteolysis in tumor metastasis and IL-4 was closely associated with OC formation, we compared the number of OCs between WT mice and IL4KO mice after injection of MC-38 cells into tibias." (PMID 34863091, 2021). "As confirmed by ELISA, treatment with ICJ inhibited the expression of IL-4 under tumor-associated conditions." (PMID 35027915, 2021). "Heterotopic-engrafted ovariectomized/castrated BALB/c mice treated with E2 featured reduced volume of tumors by suppressing the alternative activation of tumor-associated macrophages into a pro-inflammatory profile in an IL-4-Jak1-Stat6-dependent mechanism." (PMID 34771745, 2021). "For instance, IL-2, IL-15, and IL-21 are reported to promote tumor suppression in melanoma, whereas IL-1, IL-4, and IL-6 are associated with tumor progression in breast, prostate, and lung cancer." (PMID 33800170, 2021). "Consistent with the pathogenic feedback loop for IL-4, cultured cells derived from a plaque or a tumor lesion significantly increased the percentage of TOX+ CD4+ cells in the presence of recombinant IL-4." (PMID 34220814, 2021). "Tumor-secreted factors, such as IL-4, IL-10, and M-CSF, can induce the polarization of macrophages into M2-like tumor-associated macrophages (M2-like TAMs)." (PMID 33959512, 2021). "Both IL-4 and IL-13 are involved in the differentiation of macrophages into pro-tumorigenic M2, which are classified as tumor-associated macrophages (TAMs)." (PMID 34071442, 2021). "Previous studies show that T follicular helper (Tfh) cells emerge in tumor-draining lymph nodes where they produce IL4 to reduce antitumor immunity and cause myeloid cells to differentiate into M2 macrophages." (PMID 34136488, 2021). "Type 2 innate signals, such as IL-4 signal, are closely associated with tumor progression, macrophage polarization and osteoclastogenesis." (PMID 34863091, 2021). "In brief, the shift from a Th1 to a Th2 inflammatory response will lead to an increase in immunosuppressive cytokine release (IL-2, IL-4, IL-7, IL-13, and IL-15) by neoplastic elements and tumor-associated cells, sustaining tumor growth and spread." (PMID 34685762, 2021). "IL-4, IL-10 and chemokines recruit circulating monocytes leading to generation of tumor associated macrophages (TAM)." (PMID 33923976, 2021). "Tumor-derived cytokines with immunosuppressive activities, such as IL-10 and IL-4, are able to convert tumor-associated macrophages (TAMs) to polarized type 2 (M2 macrophages) that promote cancer progression." (PMID 33003428, 2020).